TNF (tumor necrosis factor)
Diseases named in the same sentence as TNF in open-access papers (continued):
Sharing a sentence is not in itself a finding about the gene and the disease.
cancer (continued). "Silencing of hPEBP4 sensitizes the cancer cells to TNF-α/tumor necrosis factor-related apoptosis-inducing ligand (TRAIL)-induced apoptosis by increasing activation of JNK (c-Jun N-terminal kinase) and the Raf-1/MEK/ERK pathway, indicating that hPEBP4 is a candidate target molecule." (PMID 23451095, 2013). "Also, Ssd revealed a significant potency of abolishing TNF-α-induced cancer cell invasion and angiogenesis in HUVECs while inducing apoptosis via enhancing the loss of mitochondrial membrane potential in HeLa cells." (PMID 23573150, 2013). "Anti-TNF treatment of RA does not increase overall cancer risk, but increases the risk of NMSC, especially when combined with methotrexate." (PMID 23987103, 2013). "TNFα-induced NF-κB pathway is a well-known molecular target for cancer therapy." (PMID 23997800, 2013). "The NF-κB activity is considered as a major factor of TNF resistance in cancer cells." (PMID 23635099, 2013). "However, despite the profound cytotoxic and cytostatic effects of TNF-α on primary tumors, its undesirable effect of activating NF-κB signaling and pro-metastatic nature, in particular, limit its use widely for cancer patients." (PMID 23573150, 2013). "The cytokines involved in cancer-related inflammation, including interleukin-6 (IL-6) and tumor necrosis factor-alpha (TNFα), may induce neutrophilia." (PMID 24223776, 2013). "Therefore, sensitizing agents capable of overcoming this undesirable effect must be valuable for facilitating the usage of TNF-α-mediated apoptosis therapy for cancer patients." (PMID 23573150, 2013). "Furthermore TNF is abundantly released in in vivo situation like chronic inflammatory disorders, as well as cancer, and a TNF inhibitor is actually useful for the control of inflammatory disorders." (PMID 23864892, 2013). "Elevated activation of NF-κB and upstream triggers such as TNF-α supports the hypothesis that this pathway plays a crucial role in cancer development." (PMID 24386633, 2013). "Sensitizing agents capable of overcoming this resistance may facilitate the establishment of TNF-α-mediated apoptosis remedy against cancers in clinic." (PMID 23573150, 2013). "Moreover, it has been described that TNF-α can induce SLex and 6-sulfo-SLex expression in human cancer cells, by increasing the expression of ST3GAL4." (PMID 23799130, 2013). "The role of TNF-α in cancer is complex with both apoptotic and anti-apoptotic roles proposed." (PMID 23339680, 2013). "However, when cancer cells were pre-treated with Vemurafenib, the release of TNF and IL-12 from poly(I:C) matured DCs was re-established to a level obtained in the control (matured DCs without cancer cells)." (PMID 24376443, 2013). "TNFα released from macrophages induces cancer cell proliferation and migration." (PMID 23818931, 2013). "Therefore, TNFα released from macrophages activates NF-κB-mediated signaling pathway in cancer, resulting in cancer progression and metastasis." (PMID 23818931, 2013). "The inverse correlation between the intensity of the inflammatory infiltrate and epithelial TNF-α in the cases of carcinoma may be responsible for the reduction in NF-κB in epithelial cells following transformation, thereby suggesting a role in this process." (PMID 23833665, 2013). "Furthermore, TNFα is frequently detected in human cancers with poor prognosis, such as ovarian, renal and breast cancers." (PMID 22675434, 2012). "TNF induced NF-κB activation is critical regulator of cell survival and death, having implications in many physiological and pathological conditions including cancer." (PMID 23152791, 2012). "We found that expression of ADCK2 and TRIB2 mRNA is regulated by TNFα in U2OS cancer cells." (PMID 22355351, 2012). "Four cancers occurred in the anti-TNF-α arm, and 1 in the placebo arm." (PMID 23155441, 2012). "For example, cancer cells arrested in mitosis by MI become extremely sensitive to TNF and TRAIL." (PMID 22802145, 2012).
cancer (continued). "We examined several cancer cell lines for HIF-1α accumulation under TNFα treatment." (PMID 22355351, 2012). "Cancer cell adhesion following AngII stimulation was also increased (2 fold) when endothelial cells were pre-activated for 24 hrs with pro-inflammatory cytokines (IFNγ and TNFα)." (PMID 22536420, 2012). "Similarly, TNFα treatment showed that Metabolic pathways and Pathways in cancer were the top two affected pathways." (PMID 22947142, 2012). "Serum TNF-α level was found to be elevated in cancer patients." (PMID 23300633, 2012). "Besides TNF-α action to suppress proliferation and induce apoptosis in a variety of cancer cells, it can also exert a growth-promoting effect on normal epithelia." (PMID 22235273, 2012). "Animal model studies demonstrate that TNFα has pro-cancer actions." (PMID 22675434, 2012). "Triptolide was shown previously to sensitize cancer cells to TNFα-induced apoptosis." (PMID 22545132, 2012). "In addition to causing mesothelial retraction, TNFα and other inflammatory mediators upregulate ICAM-1 and VCAM-1 adhesion molecules on mesothelial cells, which facilitates cancer–mesothelial cell interactions." (PMID 22527451, 2012). "Among the 94 cancers that occurred on TNF-α antagonist, 57 occurred at doses in line with NDA." (PMID 23155441, 2012). "This meta-analysis included a total of 34 articles on TNF-α-238 and cancer." (PMID 21818296, 2011). "The body redox systems, which include antioxidant enzymes and low molecular weight antioxidants, may be deregulated in cancer cells along with TNF-α and IL-6." (PMID 21350723, 2011). "We did not detect any significant association between TNF-α-238 polymorphism and cancer susceptibility in the overall population, with summary OR being 1.09 (0.88–1.34)." (PMID 21818296, 2011). "Furthermore, functional polymorphisms in TNF-α and TNFRSF1B genes that alter gene expression are likely to be associated with risk and clinical outcomes of cancers." (PMID 21995493, 2011). "Indeed, here we have obtained an important indication to the roles of TNFα in disease recurrence and progression, because there was significantly higher prevalence of TNFα in tumors of the IDC-with-relapse group than in the other two groups of cancer patients." (PMID 21486440, 2011). "Similarly, TNF inhibitors have been used for the treatment of inflammatory and autoimmune diseases, but also for the treatment of cancer." (PMID 22162712, 2011). "Another possible explanation for increased cancer growth may be systemic effects of local radiation therapy mediated by immune or inflammatory systems such as TNFα." (PMID 21527002, 2011). "Treatment with apoptosis-inducing ligands belonging to the Tumour Necrosis Factor-alpha (TNF-α) family could be an effective strategy for cancer treatment." (PMID 22136382, 2011). "Treatment with GL tended to increase mitogenic reactivity to phytohemagglutinin, counts of CD3, CD4, CD8 and CD56 lymphocytes, plasma concentrations of interleukin (IL)-2, IL-6 and interferon (IFN)-γ, and NK activity, whereas plasma concentrations of IL-1 and TNF-α were decreased in cancer patients." (PMID 19617199, 2011). "An alternative concept for the use of TNF-α in the treatment of human cancers exists." (PMID 22036896, 2011). "Moreover, plasma TNF levels are increased in some cancer patients, especially those with a poor prognosis." (PMID 24212934, 2011). "Forth, TNF-α-308 polymorphism is significantly linked with higher occurrences of TNF-α-producing autoimmune Major Histocompatibility Complex (MHC) haplotype HLA-A1, B8, DR3, which was already confirmed as a risk factor for cancers." (PMID 21818296, 2011). "TNF-α has been reported to play an important role in the pathogenesis of cancer." (PMID 21818296, 2011).
cancer (continued). "In summary, we have shown that the way in which UK rheumatologists are selecting their patients with RA and prior malignancy to receive anti-TNF therapy is not leading to an increased risk of incident malignancy over the period of followup studied." (PMID 20535785, 2010). "Mocellin and Nitti suggest that TNF α may represent one of the molecular links between chronic inflammation and further development of malignant tumors." (PMID 20640152, 2010). "In addition, in some cancer cells, TNF-α enhances cells migration and metastasis through NF-κB-dependent induction of the chemokine receptor CXCR4, monocyte chemoattractant protein-1 (MCP-1), IL-8 and intercellular adhesion molecule-1." (PMID 20087353, 2010). "Here we investigated the possibility that dNSurR9-C84A might activate the caspase-8-mediated pathway of extrinsic apoptosis, and thereby augment the efficacy of TNF-α treatment of cancer." (PMID 20920299, 2010). "In patients exposed to anti-TNFα agents we observed a non-significantly decreased risk for developing a malignancy compared to patients treated with conventional DMARDs (adjusted HR = 0.70; 95% CI: 0.44 to 1.12, P = 0.13)." (PMID 20064207, 2010). "Accumulating evidence has shown that TNF-α is a key mediator of inflammation and cancer." (PMID 20087353, 2010). "Cocktail 1 was designed as in a previous reported cocktail, where the combination of poly I:C, IFNα, IFNγ, TNFγ and IL-1β showed very potent IL-12p70 stimulating properties compared to the standard DC cocktail used for DC based cancer vaccines, containing IL-6, TNFα, IL-1β and PGE2." (PMID 20663192, 2010). "The results showed either aCD4S or the combination of IFN-γ/TNF-α could increase the radiosensitivity of these cancer cell lines to γ-irradiation." (PMID 20178622, 2010). "Interestingly, TNFα treatment in combination with NF-κB inhibition decreased cell viability in only two of the cancer cell lines (SW1736 and TPC1)." (PMID 20492683, 2010). "Clinical trial data and open-label extension studies are thus limited in their ability to address the question of whether anti-TNF therapy influences the malignancy rate in patients with prior cancer." (PMID 20535785, 2010). "TNF-α, IL-1 and IL-6 are key cytokines involved in cancer-related cachexia." (PMID 20920199, 2010). "Our data add to the growing evidence of no overall increased cancer risk for patients treated with anti-TNFα agents during the first years of treatment." (PMID 20064207, 2010). "Moreover, glutamine is necessary for the synthesis of those cytokines involved in cancer cachexia including tumor necrosis factor alpha, (TNF-α) and the interleukins 1 and 6 (IL-1 and -6)." (PMID 20181022, 2010). "Furthermore, TNF-α was found to affect the gene networks related to drug metabolism, cell cycle, cancer, neurological disease, organismal injury, and abnormalities in myotubes." (PMID 20967264, 2010). "The elevated levels of TNF α in patients with malignant tumors may be also due to activation of angiogenesis and overexpression of TNF α in the transformed cells." (PMID 20640152, 2010). "It further points to the assumption that TNF-α may be involved in H. pylori positive gastric carcinogenesis as an indispensable and strong linker between inflammation and cancer." (PMID 20699000, 2010). "There remains the possibility of surveillance bias, in which patients in the anti-TNF cohort have more frequent followup appointments and/or closer clinical scrutiny of new symptoms that might then be diagnosed as an incident malignancy." (PMID 20535785, 2010). "In humans, there is an increasing evidence that cytokines, including tumor necrosis factor alpha (TNF-α), interleukin (IL)-1, IL-6, IL-8 and interferon gamma (IFN-γ) may participate in the cause or the development of cancer cachexia." (PMID 20037740, 2009). "Our data demonstrating that over expression of miR-23a∼27a∼24-2 sensitized HEK293T cells to TNF-α cytotoxicity could potentially be of value in cancer therapy." (PMID 19513126, 2009).
cancer (continued). "Simvastatin strengthens TNF-alpha-induced apoptosis through the down-regulation of NF-κB-dependent antiapoptotic gene products, suggesting a role in the prevention and treatment of cancer cells through NF-κB modulation." (PMID 23675166, 2009). "TRPV1 has been shown to be up-regulated by TNFα in cancer-related thermal hyperalgesia in mice." (PMID 19753113, 2009). "Gene ontology, molecular network and canonical pathway analysis of NASP overexpression demonstrated that the most significant changes were in proteins participating in organismal injury, immune response, and cellular growth and cancer pathways (major "hubs": TNF, FOS, EGR1, NFκB, IRF7, STAT1, IL6)." (PMID 19439102, 2009). "In this regard, future clinical trials of MV as a new oncolytic virus to treat human cancers may provide a unique opportunity to determine the actual physiological relevance of leukocyte-based TNF and type I IFN responses in humans at the whole organism level." (PMID 18617992, 2008). "For example, the TNF network includes the activity-dependent neuropeptide protein (ADNP), a novel element of SWI/SNF chromatin remodelling complexes that downregulates TNF and may be important in immune surveillance and cancer." (PMID 18638373, 2008). "Moreover, TNF-α is involved in the complex and poorly understood process of cancer-induced cachexia or muscle wasting." (PMID 18682839, 2008). "On the other hand, it may stimulate cancer cell growth and therefore anti-TNF-α drugs have been proposed for cancer treatment." (PMID 18257926, 2008). "However, in addition to mast cells also cancer cells themselves can produce both histamine and TNF-α." (PMID 18257926, 2008). "The pro-inflammatory cytokines TNF-α, IL-1 and IL-6, by contrast, may promote cancer progression by a variety of other mechanisms, that are only now beginning to be elucidated." (PMID 18682839, 2008). "Previous studies suggest that TNF-α may be able to act synergistically with histamine in the regulation of growth of carcinoma cells and keratinocytes, but functional evidence to support this hypothesis is very sparse." (PMID 18257926, 2008). "Furthermore, TNF-α-sensitive ME-180 carcinoma cells were also resistant to the combination effect of TNF-α and histamine." (PMID 18257926, 2008). "However, both the carcinoma cells and control epithelial cells were immunostained in a similar intensity for TNF-α." (PMID 18257926, 2008). "In a study of outcomes from thoracic surgery, Shaw and colleagues genotyped six polymorphisms in five genes, finding associations for SNPs in tumor necrosis factor (TNF) and interleukin-6 (IL6) with the risk of complications in 155 patients undergoing lung resections for cancer." (PMID 17686149, 2007). "Interestingly, the genotype distribution of the -308 TNF-a genotypes for the South African cancer cases were different to those reported in a Korean population group (homozygous GG 71% vs 90%; and heterozygous AG 26% vs 6%)." (PMID 16438713, 2006). "In addition, VP-16 and the chemotherapeutic agent mitomycin were also found to induce IL-8 and TNF-α production by a human epithelial carcinoma cell line (KB cells) that expressed platelet-activating factor receptor." (PMID 17047652, 2006). "It modulates several cytokines, e.g., TNF-α only moderately and so should not do so to the degree of being a cancer causative, but its modulation is effective for restoring the cytokine balance, key for the treatment of inflammatory based diseases." (PMID 15854222, 2005). "This research, through perspective random clinical control experiment, observed the therapeutic effect of the treatment of late malignant tumor through the injection of recombinant mutant human tumor necrosis factor (rmhTNF) combined with general chemotherapy and its adverse reactions." (PMID 15485573, 2004). "Indeed, high concentrations of TNF alpha induced apoptosis for less than 25% of MDA-MB231 cancer cells." (PMID 12698185, 2003).
cancer (continued). "This explains that in cancer patients, instead of mediating cancer cell apoptosis, TNF alpha may be responsible for discomfort symptoms, such as cancer-related fatigue and weightloss." (PMID 12698185, 2003). "Also, the incubation of MDA-MB231 cancer cells with monocytes resulted in a dramatic increase in TNF alpha in supernatants (18 000%) as compared with secretion by monocytes incubated alone." (PMID 12698185, 2003). "However, MDA-MB231 cancer cells have been shown to be resistant towards the apoptotic action of TNF alpha." (PMID 12698185, 2003). "In the present study, we have sought to evaluate the role of TNF in the host response to DMXAA by utilising mice with targeted disruption of TNF receptor I gene (TNFR1−/−) as recipients for the (TNF positive) colon 38 carcinoma." (PMID 12177785, 2002). "Transcription factors like SNAIL and NF-kB, previously linked to miR-146a-5p regulation in other cancers, or rs2910164 polymorphism in pre-miR-146a reported in OSCC patients or activation of TNFα and TGF-β, may contribute to the high expression of miR-146a-5p in SCC-9 OSCC cells." (PMID 40338154, 2025). "Furthermore, cardamonin was found to inhibit TNF-α-induced NF-κB activation in cancer cell lines." (PMID 41302385, 2025). "The ‘browning’ conversion in visceral adipose tissue (VAT) may be supported by cancer cells and by the oncoinflammatory niche, which is characterized by high level of pro-inflammatory cytokines, such as interleukin 6 (IL-6) or tumor necrosis factor α (TNF-α)." (PMID 40227577, 2025). "Although our analysis was limited to cancer incidence among patients receiving TNF inhibitors and therefore cannot determine whether TNF inhibitor exposure increases risk compared with TNF inhibitor-naïve patients, comparisons with existing Korean data provide context." (PMID 41302997, 2025). "Additionally, cancer cells may produce factors that destabilize TNF-α and IFN-γ, contributing to resistance." (PMID 39883638, 2025). "Thus, we conducted a systematic review and meta-analysis of head-to-head comparative effectiveness studies of JAK inhibitors vs TNF antagonists for serious infections, malignant neoplasms, MACEs, and VTE to provide a comprehensive safety assessment across IMIDs." (PMID 40928778, 2025). "It remains plausible that targeting TNF-α may confer benefits in select patient populations, such as those experiencing cancer-related cachexia or chronic inflammatory states, but concerns regarding systemic immune suppression continue to temper enthusiasm for this approach." (PMID 41007766, 2025). "In addition, five KEGG pathways—transcriptional misregulation in cancer, tumor necrosis factor (TNF) signaling pathway, mitogen-activated protein kinase (MAPK) signaling pathway, lipid and AS, and cytokine–cytokine receptor interaction—were significantly enriched." (PMID 41583468, 2025). "Notably, the use of biologic agents, including tumor necrosis factor inhibitors, has not been shown to increase cancer risk in PsA patients." (PMID 40901477, 2025). "Interestingly, the observed strong inter-cytokine correlations, particularly between TNF-α and IL-10, in both cancer types may reflect a conserved immunoregulatory axis, but this interpretation should be viewed as exploratory." (PMID 41020868, 2025). "Once arrived in bone, cancer cells secreted several cytokines, such as parathyroid hormone‐related protein (PTHrP), interleukin‐6 (IL‐6) and tumor necrosis factor (TNF), which could serve as osteoclastogenic factors to promote osteoclast differentiation and the bone degradation process." (PMID 39980332, 2025). "The fact that TNF-α may affect TME further complicates the dual role that it plays in cancer." (PMID 40933989, 2025). "The overall relative risk of cancer with TNF inhibitor (HR = 1.0) did not increase." (PMID 40282506, 2025).